XIAP (X-linked inhibitor of apoptosis)
Description:
Multi-functional protein which regulates not only caspases and apoptosis, but also modulates inflammatory signaling and immunity, copper homeostasis, mitogenic kinase signaling, cell proliferation, as well as cell invasion and metastasis. Acts as a direct caspase inhibitor. Directly bind to the active site pocket of CASP3 and CASP7 and obstructs substrate entry. Inactivates CASP9 by keeping it in a monomeric, inactive state. Acts as an E3 ubiquitin-protein ligase regulating NF-kappa-B signaling and the target proteins for its E3 ubiquitin-protein ligase activity include: RIPK1, RIPK2, MAP3K2/MEKK2, DIABLO/SMAC, AIFM1, CCS, PTEN and BIRC5/survivin. Acts as an important regulator of innate immunity by mediating 'Lys-63'-linked polyubiquitination of RIPK2 downstream of NOD1 and NOD2, thereby transforming RIPK2 into a scaffolding protein for downstream effectors, ultimately leading to activation of the NF-kappa-B and MAP kinases signaling. 'Lys-63'-linked polyubiquitination of RIPK2 also promotes recruitment of the LUBAC complex to RIPK2. Regulates the BMP signaling pathway and the SMAD and MAP3K7/TAK1 dependent pathways leading to NF-kappa-B and JNK activation. Ubiquitination of CCS leads to enhancement of its chaperone activity toward its physiologic target, SOD1, rather than proteasomal degradation. Ubiquitination of MAP3K2/MEKK2 and AIFM1 does not lead to proteasomal degradation. Plays a role in copper homeostasis by ubiquitinating COMMD1 and promoting its proteasomal degradation. Can also function as E3 ubiquitin-protein ligase of the NEDD8 conjugation pathway, targeting effector caspases for neddylation and inactivation. Ubiquitinates and therefore mediates the proteasomal degradation of BCL2 in response to apoptosis. Protects cells from spontaneous formation of the ripoptosome, a large multi-protein complex that has the capability to kill cancer cells in a caspase-dependent and caspase-independent manner. Suppresses ripoptosome formation by ubiquitinating RIPK1 and CASP8. Acts as a positive regulator of Wnt signaling and ubiquitinates TLE1, TLE2, TLE3, TLE4 and AES. Ubiquitination of TLE3 results in inhibition of its interaction with TCF7L2/TCF4 thereby allowing efficient recruitment and binding of the transcriptional coactivator beta-catenin to TCF7L2/TCF4 that is required to initiate a Wnt-specific transcriptional program.
Synonyms: hILP; IAP-3; hIAP-3; hIAP3; API3; BIRC4; ILP-1; ILP1; MIHA; XLP2
Tractability: Small molecule: a structure with a bound ligand is known; a high-quality ligand is known; it belongs to a druggable protein family. PROTAC: UniProt records ubiquitination sites on it; ubiquitination databases record sites on it; its protein half-life has been measured; a small molecule that binds it is known.
Target class: Other cytosolic protein
Chemical probes: ML101, ML183, PD070485, PD070489, PD080929, PD080981, PD081905, PD082237, PD082301, PD082724, PD082753, PD084103, PD084441, PD085173
Gene: Protein-coding gene on chromosome X (123,859,693 to 123,913,972, forward strand). Ensembl gene ENSG00000101966.
Subcellular location: Cytoplasm; Nucleus
Subcellular location (Human Protein Atlas): Cytosol; Nucleoplasm; Nucleoli; Plasma membrane
Pathways (Reactome):
Programmed Cell Death: Activation of caspases through apoptosome-mediated cleavage; RIPK1-mediated regulated necrosis; Regulation of necroptotic cell death; Regulation of the apoptosome activity; SMAC (DIABLO) binds to IAPs; SMAC(DIABLO)-mediated dissociation of IAP:caspase complexes; SMAC, XIAP-regulated apoptotic response
Signal Transduction: Deactivation of the beta-catenin transactivating complex; Regulation of PTEN localization; Regulation of PTEN stability and activity; Regulation of TNFR1 signaling; TNFR1-induced NF-kappa-B signaling pathway; TNFR1-induced proapoptotic signaling
Cell-Cell communication: Activation of STAT3 by cadherin engagement
Gene Ontology:
Molecular function: cysteine-type endopeptidase inhibitor activity; identical protein binding; protein binding; protein serine/threonine kinase binding; ubiquitin protein ligase activity; ubiquitin-protein transferase activity; cysteine-type endopeptidase inhibitor activity involved in apoptotic process
Biological process: defense response to bacterium; DNA damage response; negative regulation of apoptotic process; negative regulation of tumor necrosis factor-mediated signaling pathway; nucleotide-binding oligomerization domain containing 1 signaling pathway; nucleotide-binding oligomerization domain containing 2 signaling pathway; positive regulation of canonical NF-kappaB signal transduction; positive regulation of canonical Wnt signaling pathway; positive regulation of JNK cascade; positive regulation of protein linear polyubiquitination; positive regulation of protein ubiquitination; positive regulation of type I interferon production; protein K63-linked ubiquitination; regulation of apoptotic process; copper ion homeostasis; regulation of BMP signaling pathway; regulation of cell cycle; regulation of inflammatory response; regulation of innate immune response; regulation of nucleotide-binding domain, leucine rich repeat containing receptor signaling pathway; regulation of apoptosis involved in tissue homeostasis; response to lipopolysaccharide
Cellular component: cytoplasm; cytosol; nucleolus; nucleoplasm; nucleus; protease inhibitor complex
Homologues: Orthologues: chimpanzee XIAP (99% identical), macaque XIAP (99% identical), rabbit XIAP (93% identical), pig XIAP (92% identical), rat Xiap (90% identical), mouse Xiap (89% identical), guinea pig XIAP (89% identical), dog XIAP (87% identical), tropical clawed frog xiap (50% identical), zebrafish xiap (35% identical), Drosophila melanogaster Diap2 (29% identical), Caenorhabditis elegans bir-2 (15% identical). Paralogues in human: BIRC3 (39% identical), BIRC2 (39% identical), BIRC6 (28% identical), NAIP (26% identical), BIRC7 (17% identical), NLRC4 (13% identical), BIRC5 (8% identical).
Diseases named in the same sentence as XIAP in open-access papers:
XIAP is named in the same sentence as 306 diseases in open-access papers, as found by Europe PMC text mining. Sharing a sentence is not in itself a finding about the gene and the disease. The quoted sentences say what the papers report.
breast carcinoma (156 papers, 2004 to 2025). "High XIAP expression has been linked to poor prognosis in a variety of cancer types, including bladder and breast cancers, and has been reported to cause resistance to chemotherapy and radiation therapy." (PMID 39852158, 2025). "Overexpression of IAPs, including X-linked inhibitors of apoptosis protein (XIAP), inhibits caspase activation in breast cancers, thereby facilitating the escape from apoptosis and the acquisition of resistance." (PMID 40843360, 2025). "RPS3, which is known to interact with NFκB, is overexpressed in breast cancer by up-regulating the X-linked inhibitor of apoptosis (XIAP)." (PMID 34873618, 2021). "Combined inhibition of PARP by olaparib and XIAP (X-linked inhibitor of apoptosis protein) by embelin synergistically cause the release of cytochrome c from mitochondria into the cytosol in breast cancer cells." (PMID 34638899, 2021). "Overexpression of X-linked inhibitor of apoptosis protein (XIAP), a potent caspase inhibitor, in breast cancer induced resistance to cetuximab-mediated ADCC in both a caspase-dependent and -independent manner (via accumulation of reactive oxygen species)." (PMID 34557197, 2021). "FOXM1 has been found to directly regulate the transcription of Survivin and the X-linked inhibitor of apoptosis protein in breast cancer cells, providing good support to our findings." (PMID 31796105, 2019). "In breast cancer, the transcription of the pro-apoptotic Bcl-2-associated death promoter (Bad) gene and X-linked inhibitor of apoptosis (XIAP) gene are downregulated by T3." (PMID 31600974, 2019). "Herein, we examined regulation of XIAP-mediated autophagy in breast cancer cells and determined the underlying molecular mechanism." (PMID 29113338, 2017). "A previous study has shown that X-linked inhibitor of apoptosis protein (XIAP) mediates anti-apoptosis in breast cancer cells." (PMID 29113288, 2017). "It was later demonstrated that TQ promoted apoptosis in breast cancer cells through X-linked inhibitor of apoptosis protein (XIAP) mediated protein kinase B (PKB), also known as Akt pathway." (PMID 27540530, 2016). "It has been reported that XIAP is upregulated in acute and chronic leukemia, prostate cancer, breast cancer, and many other cancers, thus indicating an association between XIAP overexpression and cancer development." (PMID 27447744, 2016). "The knocking down of XIAP is associated with activation of caspase-9 through Akt signal transduction in breast cancer cells." (PMID 23613836, 2013). "Previous experiments in vitro have identified that sustained overexpression of XIAP can cause acquired tumor necrosis factor-alpha related apoptosis-inducing ligand (TRAIL) resistance in MDA-231 human breast cancer cell." (PMID 21645409, 2011). "The XIAP/caspase-7 complex has been linked to chemoresistance in caspase-3-deficient breast cancer." (PMID 40078400, 2025). "The rapid and sustained downregulation of c-fos and the translocation inhibition of its homodimers AP-1 may contribute to the drug-sensitive effects by activating X-linked inhibitor of apoptosis protein (XIAP) in MCF7 breast cancer cells." (PMID 33805928, 2021). "Using multiple cell models of aggressive breast cancer, we observed that increased XIAP expression caused decreased immune-mediated caspase activation, lower ROS induction/increased antioxidant protein, and NFκB target gene transcripts in the immune/inflammatory network." (PMID 30400822, 2018). "XIAP was found to be over-expressed in 29.5% of cases and directly associated with clinical parameters such as tumor size, extra nodal extension, triple negative breast cancer and poorly differentiated breast cancer subtype." (PMID 28893228, 2017). "Targeting XIAP both alone and in combination with LY294002 induced apoptosis in vitro and caused regression of breast cancer xenografts in vivo suggesting a role of XIAP in breast cancer tumorigenesis and at the same time, identifying XIAP as a potential therapeutic target." (PMID 28893228, 2017).
breast carcinoma (continued). "Moreover, coexpression of FOXM1, survivin, and nuclear XIAP was associated with poor outcomes of women with stage III breast cancer with significantly reduced 5- and 10-year survival rates versus women with tumors without these features." (PMID 26942015, 2016). "Preclinical studies using various breast cancer in vitro and in vivo models from our group identified a critical role for the most potent caspase inhibitor, X-linked inhibitor of apoptosis protein (XIAP), in linking EGFR-mediated MAPK activation and NFκB hyperactivity." (PMID 35697736, 2022). "In our search for druggable molecular targets, we found that XIAP was over-expressed in 29.5% of breast cancer and was significantly associated with adverse clinical parameters such as large tumor size, extra-nodal extension and high tumor grade of breast cancer." (PMID 28893228, 2017). "However, when analyzing patient subgroups, they discovered that basal-like breast cancer patients with elevated XIAP expression had a significantly increased risk of tumor recurrence, suggesting that XIAP is predictive for poor relapse free survival in this patient subgroup." (PMID 25120954, 2014). "XIAP is overexpressed in a variety of malignancies, including liver, bladder, and breast cancers, and promotes proliferation and metastasis of cancer cells and drug resistance." (PMID 40133252, 2025). "Beyond taxanes, XIAP has been shown to confer resistance to Doxorubicin in breast cancer, and to cisplatin in colon, ovarian, lung, and pancreatic cancers." (PMID 40223934, 2025). "XIAP contributes to resistance against Taxol in prostate, lung, pancreatic, and breast cancers, emphasizing its involvement in protecting cancer cells from apoptosis induced by this commonly used microtubule-targeting agent." (PMID 40223934, 2025). "In vitro, the enforced expression of miR-23a downregulated XIAP expression, thereby promoting autophagy, colony formation, migration, and invasion of breast cancer cells." (PMID 38807590, 2024). "Regarding the function of USP11 in breast cancer, it, also confusingly, promotes breast cancer cell proliferation and tumorigenesis by stabilizing XIAP and cytoplasmic p21, and inhibits breast cancer cell proliferation through deubiquitination of PTEN." (PMID 39270819, 2024). "Patients co‐expressing FOXM1, survivin, and nuclear XIAP had significantly worst OS in breast cancer." (PMID 37154878, 2023). "The three co-opted E3 ligases, VHL, XIAP, and AHR, have been explored against cancer targets in PROTAC12,22,44–46, and their expression patterns in tumor and normal tissues suggest extensive future usage, such as XIAP in breast cancer." (PMID 37845222, 2023). "Overexpression of HS3ST2 can increase the proliferation and colony-forming units of the BT-20 breast cancer cell line by enhancing the expression of anti-apoptotic molecules including survivin and XIAP." (PMID 36836593, 2023). "Western blot analysis revealed that MDA-MB-231 breast cancer cells treated with Tacotanina, decreased the levels of XIAP at 24 h while the levels of cleaved-casp-3 were enhanced, such as occurred in cells treated with PTX." (PMID 36615253, 2022). "Tetrac induced the upregulation of gene expressions of both the antiangiogenic thrombospondin 1 (THBS1) and antiapoptotic XIAP in human breast cancer cells." (PMID 36005485, 2022). "And curcumin inhibits the expression of XIAP and significantly reduces the incidence of breast cancer metastasis to the lung in a human breast cancer xenograft model." (PMID 35992856, 2022). "The significantly higher expression of XIAP and survivin was in advanced tumors, demonstrating the most noteworthy prognostic importance in breast cancer." (PMID 36358282, 2022). "USP11 binds to Leu207 on the BIR2 domain of XIAP to stabilize XIAP, thereby inhibiting anoikis and apoptosis and promoting mammary tumor initiation and progression." (PMID 36551253, 2022).
breast carcinoma (continued). "Downregulation of survivin and XIAP by indirubin derivatives has also been seen in breast cancer, melanoma and CTCL cells." (PMID 34679649, 2021). "FOXM1 overexpressing breast cancer cells displayed an anti-apoptotic phenotype due to up-regulated expression of XIAP and BIRC5 anti-apoptotic genes." (PMID 33431968, 2021). "Thymoquinone combined with TAM induced apoptosis via X-linked inhibitor of apoptosis protein (XIAP) degradation and Akt inhibition and subsequent activation of caspase-9 and PARP cleavage in breast cancer cells." (PMID 35201439, 2021). "Ectopic expression of XIAP 3 prime untranslated region improves cell proliferation, tumor growth, colony formation, migration and invasion in human breast cancer." (PMID 33138314, 2020). "The degradation of endogenous OGT was found to be more susceptible to XIAP WT in HCT116 cells than in lung and breast cancer cells." (PMID 32994395, 2020). "XIAP was also reported to promote breast cancer cell proliferation, enhanced viability, and colony formation via its E3 ligase activity, leading p62 to ubiquitin-proteosome degradation." (PMID 33138314, 2020). "Similar to our findings, LCL161, a SMAC mimetic compound which can bind and antagonize IAPs including XIAP, was observed to promote both apoptosis and necroptosis in breast cancer cells." (PMID 32381104, 2020). "This study aims to identify the molecular targets of XIAP in human breast cancer cells exposed to XIAP siRNA by proteomics screening." (PMID 32537125, 2020). "For example, miR-23a accelerates autophagy and increases survival and migration of breast cancer cells by targeting XIAP." (PMID 32232005, 2020). "For instance, HSP70 is the most central family of stress proteins that recently empirical evidence introduced XIAP as a client of Hsp70 in MDA-MB-231 breast cancer cells." (PMID 32537125, 2020). "For example, the microRNA miR-23a was found to be a negative regulator of XIAP (i.e. downregulates the expression) and overexpression of miR-23a was shown to upregulate the endogenous autophagic levels of breast cancer cells in a XIAP-dependent manner." (PMID 32019552, 2020). "The expression of XIAP in breast cancer cells is regulated by FOXM1 which acts as an intermediate between XIAP and OGT52,53." (PMID 32994395, 2020). "It has been reported that XIAP is overexpressed in acute and chronic leukemia, prostate cancer, breast cancer, and many other cancers." (PMID 31240993, 2019). "Although classically described as inhibitors of apoptosis, cIAP-1, XIAP, Mcl-1, and survivin have been shown to modulate cell migration and metastasis in cancer models, including breast cancer." (PMID 31614718, 2019). "SAHA induced autophagy and restrained cell viability through reducing survivin and XIAP protein stability in human breast cancer cells." (PMID 31683883, 2019). "MiR-429 inhibits the migration and invasion of breast cancer cells, and induces apoptosis by targeting XIAP in triple-negative breast cancer." (PMID 29715309, 2018). "Forced expression of miR-23a significantly decreased the expression of XIAP and promoted autophagy, while down-regulation of miR-23a increased XIAP expression and suppressed autophagy in breast cancer cells." (PMID 30266744, 2018). "In breast cancer cells, NF-κB has been linked to resistance and CYR61-induced resistance via p65-dependent XIAP upregulation in MCF-7 breast cancer cells." (PMID 29364834, 2018). "While XIAP over-expression was found to have poor overall survival and can be used as a viable prognostic marker in breast cancer, we were also interested in utilizing XIAP expression as a therapeutic target in breast cancer." (PMID 28893228, 2017). "The role of XIAP in breast cancer and clear-cell ovarian cancer has been elucidated by RNA interference method." (PMID 29221164, 2017).